LRP1 (LDL receptor related protein 1)
Diseases named in the same sentence as LRP1 in open-access papers (continued):
Sharing a sentence is not in itself a finding about the gene and the disease.
atherosclerosis (continued). "LRP1 has emerged as a key player in atherosclerosis, influencing protective and detrimental pathways." (PMID 40823653, 2025). "This is supported by previous research showing that LRP1 is predominantly expressed in monocytes and plays a crucial role in atherosclerosis progression." (PMID 40083817, 2025). "LRP1 is a multifunctional transmembrane receptor that plays a role not only in lipoprotein metabolism but also in the progression of atherosclerosis, myocardial ischemia-reperfusion, and ventricular remodeling." (PMID 40083817, 2025). "(iii) Loss of macrophage-associated phagocytic receptors: during the progression of atherosclerosis, macrophage-related phagocytosis receptors such as CD36, Merk, and LRP1 are lost, resulting in diminished macrophage efferocytosis." (PMID 41590849, 2025). "In a mouse model of atherosclerosis, LRP1 was shown to inhibit the expression of inflammatory mediators such as CCL2 and MMP-9." (PMID 40564911, 2025). "In VSMCs, knockout of LRP1 makes individuals more prone to cholesterol-induced atherosclerosis via the signaling pathways of platelet-derived growth factor receptor (PDGFR) and TGF-β." (PMID 39524227, 2024). "It has been shown that LRP1 is also engaged in atherosclerosis development, specifically in atherogenic plaque formation." (PMID 37020553, 2023). "In the case of atherosclerosis, lipopolysaccharide and other inflammatory mediators specifically promote LRP1 shedding." (PMID 37020553, 2023). "Mouse model of atherosclerosis is a perfect representation for LRP1-driven efferocytosis of macrophages." (PMID 37020553, 2023). "Low-density lipoprotein receptor-related protein 1 (LRP1) plays a crucial role in atherosclerosis progression." (PMID 37635956, 2023). "We also found that LRP1 is ubiquitously expressed by multiple cells, LRP1 limits atherosclerosis by blocking the PDGF signaling pathway, and there was PDGF receptor expression in the oocytes and granulosa cells." (PMID 36830452, 2023). "Some mutated genes are related to atherosclerosis, such as FAAH, KALRN, ATP10D, CUBN, APOA5, and LRP1." (PMID 36071494, 2022). "On the other hand, LRP1 can help to suppress atherosclerosis by inhibiting the PDGF-β signaling pathway and blocking the cell proliferation of VSMCs." (PMID 35958411, 2022). "It has been demonstrated that LRP1 is involved in the atherosclerosis development and atherogenic plaque formation." (PMID 35958411, 2022). "Several studies have shown that LRP1 plays a dual role in the development and regression of atherosclerosis." (PMID 35958411, 2022). "In contrast, a study using a LRP1Y63F knock-in mouse model that carries a point mutation that impedes LRP1 phosphorylation and subsequent signal transduction has highlighted a role for LRP1 in promoting atherosclerosis." (PMID 34876704, 2022). "Overall, the results of these studies reveal that in VSMCs, LRP1 plays a major role in maintaining the integrity of the vascular wall and reducing atherosclerosis by suppressing the PDGFRβ and TGFβ signaling pathways." (PMID 34124208, 2021). "The results of some studies indicated that in VSMCs, LRP1 helps to suppress atherosclerosis by inhibiting the platelet-derived growth factor (PDGF) signaling pathway." (PMID 34124208, 2021).
atherosclerosis (continued). "LDL receptor-related protein-1: a regulator of inflammation in atherosclerosis, cancer, and injury to the nervous system." (PMID 33566965, 2021). "Other recent work has developed antibodies against CR8/CR9 domain in the cluster II of LRP1, which are crucial for the interaction of this receptor with atherogenic lipoproteins, to prevent foam cell formation and atherosclerosis development." (PMID 34203120, 2021). "In this review, we summarized the dual and opposing roles of LRP1 in atherosclerosis in vivo and in vitro." (PMID 34124208, 2021). "LRP1 has been postulated to participate in numerous diverse physiological and pathological processes ranging from plasma lipoprotein homeostasis, atherosclerosis, tumor evolution, and fibrinolysis to neuronal regeneration and survival." (PMID 34124208, 2021). "On the other hand, by the use of antibodies against the CR8/CR9 domain in the cluster II of LRP1, foam cell formation and atherosclerosis development was prevented." (PMID 34203120, 2021). "This review highlights the influence of LRP1 during atherosclerosis development, focusing on its dual role in vascular cells and immune cells." (PMID 34124208, 2021). "The role of the intracellular NPxYxxL motif of the LRP1-ICD in the development of atherosclerosis has attracted increasing attention." (PMID 34124208, 2021). "In summary, LRP1 plays an antiatherosclerotic role in VSMCs, and its absence promotes atherosclerosis development." (PMID 34124208, 2021). "A leading candidate was LRP1, associated in human and animal studies with protection against AAA and atherosclerosis." (PMID 33784254, 2021). "Numerous genetic studies have demonstrated the dual roles of LRP1 in atherosclerosis-related cells in different animal models." (PMID 34124208, 2021). "A similar result was observed in adipocytes, where adipocyte-specific LRP1 knockout (adLRP1–/–) mice fed a western diet for 16 weeks exhibited a 3-fold increase in atherosclerosis and enhanced inflammation in adipose tissues compared to adLRP1+/+ mice." (PMID 34124208, 2021). "LRP1 gene deletion promotes the progression of atherosclerosis for progressive plaques, while promotes the regression of atherosclerosis for established plaques." (PMID 34124208, 2021). "Interestingly, in another model of LRP1 NPxY mutant mice, in which the tyrosine residue in distal NPxY motif was mutated to phenylalanine, the LRP1 NPxF mutation was found to increase macrophage cholesterol accumulation and promote inflammation to accelerate atherosclerosis." (PMID 33500241, 2021). "LRP1 can also protect against atherosclerosis by regulating the expression of ATP-binding cassette transporter A1 (ABCA1)." (PMID 34124208, 2021). "LRP-1 also plays an essential role in vascular homeostasis, by having a protective role in atherosclerosis pathogenesis and aneurysm formation." (PMID 34680548, 2021). "Many studies using cultured cells and in vivo animal models have revealed the important roles of LRP1 in vascular remodeling, foam cell biology, inflammation and atherosclerosis." (PMID 34124208, 2021). "LRP-1 is critical for lipid metabolism and plays an essential, although complex (mainly protective), role in atherosclerosis." (PMID 34359938, 2021). "Accompanied by enhanced levels of IL-1β and IL-6, a deficiency of macrophage scavenger receptor class B type I (SR-BI) and macrophage LRP-1 increases cell death and inflammation in atherosclerosis." (PMID 32346605, 2020). "Genetic reduction of LRP-1 in ApoE–/–/LysM-DKO-LRP1fl/+ mice restored atherosclerosis and confirmed the interaction between LRP1 and epsins in atherosclerosis." (PMID 33363178, 2020).
atherosclerosis (continued). "The aim of this work was to study the potential therapeutic relevance of a LRP1 (CR9)-specific blockade with anti-P3 Ab to counteract HFD-induced atherosclerosis." (PMID 32194867, 2020). "Mechanistically, epsins bind IP3R1 in the endothelium and LRP-1 in macrophages via their UIM domain to potentiate atherosclerosis." (PMID 33363178, 2020). "LRP1 is a key signaling protein and involved in various diseases, such as neurodegenerative diseases, atherosclerosis, and cancer." (PMID 32047813, 2020). "One mechanism is linked to impaired efferocytosis in advanced atherosclerosis via the proteolytic cleavage of the key receptors, MERTK and LRP1, which increase plaque necrosis." (PMID 32346605, 2020). "As we recently reported, deletion of macrophage epsins reduces atherosclerosis progression by preventing LRP-1, an anti-inflammatory protein involved in receptor-mediated endocytosis and protein degradation." (PMID 32770009, 2020). "LRP1 has a multitude of direct roles in lipid and cholesterol metabolism, glucose homeostasis, inflammation, and atherosclerosis." (PMID 32756554, 2020). "LRP1 not only plays a major role in protecting against atherosclerosis by reducing inflammation and removing apoptotic cells from lesions through phagocytic cells, but also interacts with MBL224." (PMID 33374290, 2020). "In a murine model of atherosclerosis, macrophage-specific LRP1 deletion enhanced atherosclerotic plaque development and intralesional inflammation and cellularity." (PMID 31080804, 2019). "In this review, we summarize existing perspectives and the latest innovations concerning the role of tissue-specific LRP1 in lipoprotein and glucose metabolism, and examine its ability to mediate inflammatory processes related to MetS and atherosclerosis." (PMID 29914093, 2018). "ShcA is an adaptor protein that binds to the cytoplasmic tail of receptor tyrosine kinases and of the Low Density Lipoprotein-related receptor 1 (LRP1), a trans-membrane receptor that protects against atherosclerosis." (PMID 29540796, 2018). "Various studies have suggested that LRP1 expressed in adipose tissues, in particular in the perivascular area surrounding the vessel wall, also plays a critical role in atherosclerosis development." (PMID 29914093, 2018). "This elegant study emphasizes the complex role of LRP1 in both the development and regression of atherosclerosis." (PMID 30524198, 2018). "It has been proposed that LRP1 is a key molecular factor that protects against the development and progression of atherosclerosis." (PMID 29914093, 2018). "Instead, a cell autonomous effect of Lrp1 tyrosine phosphorylation in macrophages is primarily responsible for increased atherosclerosis." (PMID 29144234, 2017). "We have generated a novel knock-in mouse model to investigate the physiological role of tyrosine phosphorylation at the distal NPxY motif within the cytoplasmic domain of LRP1 and its effect on staving off atherosclerosis." (PMID 29144234, 2017). "Vascular smooth muscle cells (vSMCs) protect the vessels from proteolytic injury due to atherosclerosis development by highly expressing endocytic LDL receptor-related protein-1 (LRP-1), and by producing anti-proteases, such as Protease Nexin-1 (PN-1)." (PMID 27445860, 2016). "Despite the increased cholesterol content of LRP1-expressing macrophages, studies have revealed that macrophage LRP1 protects the vasculature from the development of atherosclerosis and from excessive remodeling upon injury." (PMID 26061292, 2015). "We also have demonstrated that LRP-1 mediates tPA-induced p90RSK activation in fibroblasts, which has been shown to promote endothelial dysfunction and atherosclerosis in a diabetic model." (PMID 25514242, 2014). "Generally, macrophage LRP-1 is considered to protect against atherosclerosis, which has been verified in various models including macrophage LRP deficiency in either an LDL receptor knockout or apolipoprotein E/LDL receptor double knockout mice." (PMID 25514242, 2014).
atherosclerosis (continued). "Overall, the experiments indicate that LRP1 plays an important role in protecting the integrity of the vascular wall and preventing atherosclerosis by suppressing PDGFR activation." (PMID 23922991, 2013). "The importance of smooth muscle cell expression of Lrp1 in vascular homeostasis is best illustrated by observations that smooth muscle-specific inactivation of Lrp1 in mice exaggerates atherosclerosis severity and aortic aneurysm in hypercholesterolemic mice." (PMID 24312398, 2013). "Inactivation of the Lrp1 intracellular NpxYxxL motif enhances post prandial dyslipidemia and atherosclerosis, and increases proapoptotic effects via increased secretion of TNFα in macrophages." (PMID 22384159, 2012). "Studies published thus far have demonstrated that LRP1 inactivation is correlated with deleterious effects on atherosclerosis." (PMID 22701627, 2012). "Within macrophages, LRP1 has been shown to reduce the extent of atherosclerosis in LDL receptor/apoE double knockout mice and in LDL receptor knockout mice." (PMID 22174911, 2011). "Further, hepatic deletion of LRP1 also led to increased atherosclerosis indicating that hepatic LRP1 function also regulates the development of atherosclerosis." (PMID 22174911, 2011). "In conclusion, the current study reveals a novel PI3K-dependent mechanism by which LRP1 is essential for controlling the integrity of the vascular wall, and by which this multifunctional receptor potently protects against atherosclerosis and Marfan syndrome." (PMID 19742316, 2009). "Low density lipoprotein receptor-related protein 1 (LRP1) protects against atherosclerosis by regulating the activation of platelet-derived growth factor receptor β (PDGFRβ) in vascular smooth muscle cells (SMCs)." (PMID 19742316, 2009). "Apart from a partially overlapping epidemiology and an altered cholesterol homeostasis, atherosclerosis and AD have also been found to share genetic risk factors, including APOE and LRP1." (PMID 18987747, 2008). "Cumulative evidence indicates that the ectodomain of LRP-1 undergoes proteolytic cleavage at the cell surface, in several pathological conditions, including atherosclerosis, neuroinflammation, Alzheimer’s disease, lung inflammation and acute respiratory distress syndrome (ARDS)." (PMID 40564911, 2025). "LRP1 has an important effect on the maintenance of normal efferocytosis, and abnormal LRP1 function may directly contribute to the development of atherosclerosis lesions." (PMID 41590849, 2025). "Moreover, knockout of espins, which are important in clathrin-mediated endocytosis in myeloid cells, reduced the uptake of oxLDL through LRP1 and reduced the process of atherosclerosis." (PMID 38638885, 2024). "Furthermore, recent study has revealed that the enhancing phagocytosis of macrophages by CD47 relies on LRP1 to internalize during atherosclerosis." (PMID 38638885, 2024). "LRP1 has a protective function against atherosclerosis through modulating ATP-binding cassette A1 (ABCA1) expression via extracellular regulated protein kinases 1/2 (ERK1/2)/cytosolic phospholipase A2 (cPLA2/)arachidonic acid, an inhibitor of ABCA1 expression driven by liver X receptors (LXR)." (PMID 39524227, 2024). "Similarly, LRP1, progressively downregulated during atherosclerosis, can also be rendered inactive through ADAM17-mediated proteolytic cleavage akin to MerTK." (PMID 39660125, 2024). "Epsins promote the development of atherosclerosis by preventing the ubiquitination and degradation of LRP-1 in macrophages and regulating calcium release from the ER by promoting the proteasomal degradation of IP3R1 through its ubiquitin interaction motif (UIM) in endothelial cells." (PMID 39524227, 2024). "That loss of Tβ4, a molecular regulator of LRP1 endocytosis, recapitulates the phenotype of LRP1-depleted VSMCs emphasises the importance of controlled receptor trafficking in determining medial VSMC responses and progression of AAA and atherosclerosis." (PMID 37724952, 2023).
atherosclerosis (continued). "Furthermore, LRP-1 has been shown to play a major role in the process of atherosclerosis by mediating endocytosis of LDL particles." (PMID 36831299, 2023). "In addition to clearance of the apoptotic cells during atherosclerosis, high expression of LRP1 on macrophage can also inhibit inflammation." (PMID 37020553, 2023). "We therefore sought to determine whether Tβ4 functions to protect against atherosclerosis by regulating LRP1-PDGFRβ signalling to preserve VSMC phenotype." (PMID 37724952, 2023). "Having identified Tβ4 as a regulator of LRP1-mediated endocytosis to protect against aortic aneurysm, we sought to determine whether Tβ4 may additionally function to protect against atherosclerosis, by regulating LRP1-mediated growth factor signalling." (PMID 37724952, 2023). "To analyze the cell surface LRP1 expression in circulating monocytes at early stages of atherosclerosis we enrolled asymptomatic individuals with SCA criteria (SCA group; n = 82) and compared to individuals with low (LR group; n = 21) and intermediate (IR group; n = 124) risk factors of CVD." (PMID 35958411, 2022). "Animal experiments about effects of deletion of LRP1 on atherosclerosis lesions." (PMID 34124208, 2021). "Indeed, beyond its effects on LDL metabolism, several studies have demonstrated the existence of additional roles of PCSK9 in different stages of atherosclerosis through its interaction with other receptors, such as LRP1, ApoER2, and CD36." (PMID 34070931, 2021). "In terms of established plaques, inhibiting LRP1 in macrophages with blocking antibodies could accelerate plaque regression, potentially alleviating atherosclerosis and related cardiovascular and cerebrovascular complications." (PMID 34124208, 2021). "Therefore, it can be used to treat pathological retinal angiogenesis induced by diabetic retinopathy and atherosclerosis by regulating the expression and function of LRP1 in endothelial cells." (PMID 34124208, 2021). "In addition, several studies have revealed that LRP1 expressed in the VSMCs and macrophages protects the vasculature against the development of atherosclerosis." (PMID 34124208, 2021). "LRP1 is involved in vascular remodeling, inflammation, differentiation, and cell migration, roles shared with Tβ4, and has been shown in animal studies to protect against aneurysm and atherosclerosis." (PMID 33784254, 2021). "Therefore, macrophage LRP1 can also lead to atherosclerosis progression by promoting foam cell formation." (PMID 34124208, 2021). "As a result, the opposite effect of LRP1 involved in the regulation of atherosclerosis might depend on whether the plaque is growing or shrinking." (PMID 34124208, 2021). "This review may provide a basis for the development of new therapeutic approaches for atherosclerosis that target LRP1 and its downstream cellular signaling pathways." (PMID 34124208, 2021). "The dual and opposing roles of LRP1 may also represent an interesting target for atherosclerosis therapeutics." (PMID 34124208, 2021). "Therefore, in VSMCs, LRP1 can also promote atherosclerosis development by promoting the formation of foam cells." (PMID 34124208, 2021). "Furthermore, LRP1 also regulates cholesterol accumulation in macrophages, promoting their transformation into foam cells and leading to atherosclerosis." (PMID 34124208, 2021). "However, the role of macrophage LRP1 in atherosclerosis is controversial, as macrophage LRP1 not only protects against but also promotes atherosclerosis." (PMID 34124208, 2021). "LRP1 and ApoC1 accelerate the development of atherosclerosis through different pathways." (PMID 32953262, 2020). "The current view of the role of LRP1 in atherosclerosis formation is controversial." (PMID 32455133, 2020).